SFRP2 (secreted frizzled related protein 2)
Diseases named in the same sentence as SFRP2 in open-access papers (continued):
Sharing a sentence is not in itself a finding about the gene and the disease.
tumor (continued). "Our findings suggest a possible interaction between SFRP2 methylation levels and BMI in CRC tumor samples." (PMID 31319558, 2019). "In adjacent non-tumor tissues, the number of patients with SFRP1, SFRP2, and WIF1 methylation levels exceeding the cut-off value were 5 (2.7%), 7 (3.7%) and 41 (21.9%), respectively." (PMID 31830937, 2019). "In this study we discovered that SFRP2 was hypermethylated in CRC tumor tissue, when compared to adjacent tumor-free tissue areas." (PMID 31319558, 2019). "For further survival analysis, the cut-off values of SFRP1, SFRP2, and WIF1 methylation for distinguishing the survival status accounted for 10.0, 50.0, and 50.0% in tumor tissues." (PMID 31830937, 2019). "The cut-off values of SFRP1, SFRP2, and WIF1 methylation were 10.0, 5.0 and 20.0%, respectively, which had high predictive ability to distinguish tumor tissues from adjacent non-tumor tissues." (PMID 31830937, 2019). "Collectively, we conclude that TET1 exerts its anti-tumor functions in NPC cells by suppressing Wnt/β-catenin signaling via demethylation of Wnt antagonists (DACT2 and SFRP2)." (PMID 30075814, 2018). "In fact, SFRP2 and SFRP4 expression is often increased in tumours and are tightly correlated to Stromal Scores, suggesting that their expression is produced by the tumour stroma." (PMID 28218291, 2017). "The percentage of methylated reference (PMR) levels of SFRP1, SFRP2, PRKCB and WIF1 in 111 NSCLC tumor tissues and 111 paired adjacent tissues were quantified by SYBR green-based quantitative methylation-specific PCR (qMSP)." (PMID 28422739, 2017). "By subtracting the ‘free-flowing’ TIC from the tumor TIC, we established ‘free-flowing-corrected’ TICs (ffc-TICs) for SFRP2 and ffc-TICs for IgY-targeted contrast." (PMID 28333964, 2017). "Our gene regulation, DNA methylation, cell growth, and colony formation results indicate that SFRP2 and SFRP5 both act as tumour suppressors of MPM and are silenced by DNA hypermethylation." (PMID 29386699, 2017). "SFRP2 and SFRP5 tumour-suppressive activity in eleven MPM lines was confirmed, and long-term asbestos exposure led to reduced expression of the SFRP1 and SFRP2 genes in the mesothelium (MeT-5A) via epigenetic alterations." (PMID 29386699, 2017). "A previous study confirmed that the epigenetic inactivation of SFRP2, a member of the SFRP family, is important in the progression of several types of human tumor, including head, colorectal and breast cancer." (PMID 25189527, 2014). "Through MSP, the methylation status of the SFRP2 promoter was evaluated in 49 cases of OSCC and corresponding normal tumor-adjacent tissues." (PMID 25189527, 2014). "Concordantly hypermethylated CpGs were associated with genes involved in Cadherin, Wnt and Notch signaling pathways, many of which have been previously reported as frequently methylated in a variety of neoplasms, such as APC2, SFRP2, CDH13, CDH15 and PCDH10." (PMID 22737091, 2012). "We had some success in suppressing C4-2B tumor proliferation and promoting apoptosis with MSC-targeted SFRP2 expression." (PMID 20886110, 2010). "To date, four SFRP family genes (SFRP1, SFRP2, SFRP4 and SFRP5) and two DKK family genes (DKK1 and DKK3) have been identified as targets of epigenetic silencing in human tumours." (PMID 18283316, 2008). "This validation revealed cell type-specific expression patterns: SFRP2 was predominantly expressed in fibroblasts, AQP1 localized to proximal tubular cells, vasa recta, and bud-like epithelial cells, while REN was primarily expressed in tumor cells." (PMID 40534868, 2025). "Moreover, we identified five molecules (SCGB1B2P, SFRP2, POSTN, COL3A1, ENTPD6) that were universally overexpressed in medullary cells infiltrated by IBC tumours." (PMID 40624675, 2025).
tumor (continued). "In addition to the tumor cells (dsRED+), we also found another cell cluster lacking the expression of dsRED that similarly express mesenchymal genes, but which was enriched for additional genes previously associated with CAFs, such as Rarres2, Pi16, Fap, Lum, Sfrp2, Dpt, and Col14a1 5,35." (PMID 38509063, 2024). "In summary, the pro-angiogenic effect of SFRP2 largely depends on the non-canonical Wnt signaling pathway, potentially through direct binding to the FzD5 receptor on tumor endothelial cells." (PMID 39850884, 2024). "Combined with previous single-cell sequencing results, we further confirmed that SFRP2 is involved in genes related to the STAD tumor microenvironment and may participate in vascular-related tumor functions or processes." (PMID 39850884, 2024). "In multivariate analysis, tumour AHRR and SFRP2 remained independent prognostic markers." (PMID 38361045, 2024). "In this study, we identified high expression of SFRP2 in mural cells (especially pericytes) in AEGJ liver metastasis, suggesting that SFRP2 may influence the tumor microenvironment and liver metastasis by regulating pericyte function." (PMID 39850884, 2024). "Similarly, we observed that the concentration of SFRP2 was the highest in LCC compared to SCC and AC, in tumour samples, as well as in NT specimens." (PMID 37999144, 2023). "Similarly, some studies reported decreased SFRP2 protein levels in NSCLC specimens and NSCLC cell line A549 compared to non-tumour samples and pulmonary epithelial cell line BEAS-2B, respectively." (PMID 37999144, 2023). "To address this issue, we performed single-cell analysis and found that SFRP2 is predominantly expressed in a unique subset of CAF in single-cell RNA-seq data from OC patients with nonmalignant tumor tissues and HGOSC tissues." (PMID 38069266, 2023). "We identified significant enrichment of Fib-APSN and Fib-SFRP2 in tumor boundary and non-malignant regions, respectively." (PMID 36806082, 2023). "In contrast, expression of C3, SFRP2, STAT3, IL-6 and THY1 was increased in tumor-distal stroma." (PMID 37350578, 2023). "It is able to induce apoptosis of various tumor cells in vitro by regulating many signaling pathways, such as caspase family proteins, transforming growth factor (TGF) receptor, Smad 4 protein, and secreted frizzled-related protein 2 (SFRP2)." (PMID 36532760, 2022). "SFRP2 is a secreted key inhibitor of non-canonical Wnt signaling and is considered a tumor suppressor gene depending on the organ/cellular context." (PMID 35892888, 2022). "ARID5B, BAZ2B, RABGAP1, SFRP2, and WBP1L have not been previously associated with MS risk, and all are associated with neoplastic diseases and cellular proliferation." (PMID 36685876, 2022). "This review discusses the role of SFRP2 in noncanonical Wnt signaling and tumor angiogenesis, and highlights its potential as anti-angiogenic therapeutic target in cancer." (PMID 33140138, 2021). "This tumor promoting effect can likely be contributed to the upregulation SFRP2 on the tumor vasculature and, consequently, activation of the noncanonical Wnt/Ca2+ pathway." (PMID 33140138, 2021). "The upregulation of SFRP2 can enhance noncanonical Wnt/Ca2+ signaling, resulting in enhanced tumor angiogenesis, a crucial step in tumorigenesis." (PMID 33140138, 2021). "Indeed, SFRP1, SFRP2 and SFRP5 genes were frequently hypermethylated in OSCC cell lines and in primary tumor samples, while their ectopic expression suppressed the growth of OSCC cells in vitro." (PMID 32183420, 2020). "Additionally, SFRP2 was found methylated in the majority of OSCC samples, in contrast to corresponding normal mucosa, and its overexpression reduced tumor growth in vivo." (PMID 32183420, 2020). "Patients who received treatment displayed lower SFRP2 methylation levels than those without treatment, within the tumor tissue, though not in the tumor-free area." (PMID 31319558, 2019).
tumor (continued). "As a total of 307 sporadic postoperative CRC patients were followed up, we detected SFRP1, SFRP2, and WIF1 methylation obtained from tumor tissues and adjacent non-tumor tissues respectively on the basis of methylation-sensitive high resolution melting analysis." (PMID 31830937, 2019). "We also observed a significant negative correlation between global LINE-1 and SFRP2 methylation in CRC tumor tissue (r = −0.329, p = 0.011)." (PMID 31319558, 2019). "SFRP1, SFRP2, and WIF1 were frequently hypermethylated in CRC tumor tissues." (PMID 31830937, 2019). "In order to investigate whether adiposity affects DNA methylation levels, the methylation pattern of SFRP2 and LINE-1 was compared in tumor tissue and tumor-free area, in both BMI groups." (PMID 31319558, 2019). "The promoter of SFRP1, SFRP2, and WIF1 were frequently hypermethylated in CRC tumor tissues." (PMID 31830937, 2019). "We have successfully demonstrated that the beneficial association of tumor SFRP2 hypomethylation is dependent on patient BMI in non-treated CRC, suggesting a possible tumor suppressor role for SFRP2 in overweight and obese patients." (PMID 31319558, 2019). "PAX6 upregulates a known tumor suppressor PTEN, as well as SFRP2 - an inhibitor of the WNT pathway." (PMID 29568088, 2018). "SFRP1, SFRP2 and PRKCB methylation levels could discriminate NSCLC tissues from adjacent non-tumor samples." (PMID 28422739, 2017). "Surprisingly, SFRP2 mRNA is highly expressed in tumor-adjacent normal tissues, but not in tumor samples." (PMID 28708091, 2017). "We demonstrate that sFRP2 expression strongly enhances metastatic potential both in vitro and in vivo, but has no noted effects on tumor cell proliferation or primary tumor development." (PMID 27821163, 2016). "Our manuscript mainly discussed the average methylation rate of SFRPs (SFRP1, SFRP2, SFRP4, and SFRP5) promoters are significantly high in tumor tissue samples and the average CpG island methylation rate among different pathological levels of cutaneous SCC between these genes are different." (PMID 26394929, 2015). "Of these, CAV1, SFRP2, TMEFF2, SST and SLIT2 have been identified as tumor-suppressor genes." (PMID 25997610, 2015). "In order to investigate whether SFRP2 affects the growth of OSCC via the Wnt signaling pathway in nude mice, the expression levels of GSK-3β, β-catenin and cyclin D1 in tumor tissues were further analyzed by immunohistochemical analysis." (PMID 25189527, 2014). "Third, SFRP1, but not SFRP2, is a potent angiogenic factor independent of Wnt signalling, suggesting its upregulation enhances tumor vascularisation." (PMID 22384081, 2012). "Since both DKK1 and sFRP2 are established targets of TCF/β-catenin-mediated transcription, these findings suggests the presence of a negative feedback loop in MM in which DKK1 and sFRP2 act as potential tumor suppressors." (PMID 22363428, 2012). "Tumor samples from 155 patients with stages IIIB to IV NSCLC who received EGFR-TKI therapy were analyzed for DNA methylation status of Wnt antagonist genes, including SFRP1, SFRP2, SFRP5, DKK3, WIF1, and APC, using methylation specific PCR (MSP) method." (PMID 23009178, 2012). "However, the upregulation of ten–eleven translocation methylcytosine dioxygenase 1 (TET1) has been reported to suppress tumor cell survival, migration, and invasion via the activation of Wnt antagonist, dishevelled binding antagonist of beta catenin 2 (DACT2), and SFRP2." (PMID 37932756, 2023). "Consistent to our report, the gene expression level of SFRP2 was significantly lowest in the tumor area and highest at a 1-cm distance in both proximal and distal sides, indicating that there was a biomolecular response of NAT to inhibit the tumor lateral growth of primary cancer." (PMID 38062443, 2023).
tumor (continued). "One of them, SFRP2, is a member of the secreted frizzled-related protein (SFRP) family and a typical regulatory protein of the WNT pathway; it has been reported as a co-factor for ten-eleven translocation 1 (TET1), contributing to the inhibition of tumor metastasis." (PMID 38069266, 2023). "However, tumor promoting roles for SFRP1 and SFRP2 have been reported in cancer." (PMID 37091166, 2023). "However, recent study has indicated that SFRP2 can promote tumor angiogenesis via the noncanonical Wnt/Ca2+ signaling." (PMID 35372028, 2022). "As this N-terminal cysteine-rich domain shares substantial sequence similarity with Wnt binding domain of FZD receptors, SFRP2 was initially considered to antagonize the Wnt signaling by preventing binding of Wnt ligands to FZD receptors, which may inhibit tumor development." (PMID 35372028, 2022). "SFRP2-induced angiogenesis and tumor growth is not mediated through β-catenin." (PMID 34070758, 2021). "In tumor models, the pro-angiogenic effect of SFRP2 could be counteracted by antibodies targeting SFRP2, without the occurrence of toxicity." (PMID 33140138, 2021). "Thus, although extensive methylation in MGMT and SFRP2 has a similar feature in terms of association with CRC with KRAS mutations, all POLE-mutant tumours demonstrated extensive methylation in SFRP2, but no methylation in MGMT." (PMID 34034807, 2021). "Indeed, treatment of mice with an anti-SFRP2 antibody shows specific antibody binding to the tumor vasculature but not normal vessels." (PMID 33140138, 2021). "In CRC patients who are below of 30th percentile of vitamin D, SFRP2 methylation did not correlate with methylation of colorectal carcinogenesis genes, although SFRP2 methylation in tumor area was positively correlated with SFRP2 methylation in tumor-free area (p < 0.05)." (PMID 32517740, 2020). "We demonstrated that the DNA methylation levels of SFRP2 are lower in overweight/obese patients, in comparison with non-obese patients, specifically in tumor areas, supporting the hypothesis that BMI could play a protective role in the development of CRC." (PMID 31319558, 2019). "Therefore, despite the stromal contribution of SFRP2 and/or SFRP4, hypermethylation within the tumour cell compartment may still show utility as a clinical biomarker." (PMID 28218291, 2017). "Interestingly, alterations in sFRP2 expression did not alter OS proliferation rates or primary tumor development." (PMID 27821163, 2016). "Notably, a specific subtype of tumor cells enriched in tumor metastases are able to undergo EMT and further differentiate into growth-regulated oncogene-α-positive (CXCL1+) CAFs, which subsequently mature into secreted frizzled-related protein 2-positive (SFRP2+) CAFs." (PMID 41450739, 2025). "In contrast to AHRR and SFRP2 other markers did not maintain significance in multivariate analysis or could not be confirmed as being differentially expressed between primary and recurrent tumours on the protein level." (PMID 38361045, 2024). "However, there is a discrepancy in which several studies have shown that SFRP2 is an agonist (rather than an antagonist) of β-catenin suggesting the reverse: that SFRP2 may promote tumor growth." (PMID 24489757, 2014). "Conversely, SFRP2 and AQP1 were not confined to tumor regions, reaffirming their non-specific expression patterns observed in single-cell analysis." (PMID 40534868, 2025). "In this study, a lower level of protein SFRP2 was observed in the total NSCLC group’s samples, as well as in SCC and AC tumours compared to non-tumour samples." (PMID 37999144, 2023). "The aim of this study was to evaluate the concentrations of SFRP1, SFRP2, and SFRP5 proteins in tumour and non-tumour (NT) samples obtained from 65 patients with primary NSCLC." (PMID 37999144, 2023). "We investigated the SFRP2 methylation in peripheral blood mononuclear cells (PBMCs), visceral adipose tissue (VAT), CRC tumor tissue, and adjacent tumor-free area." (PMID 32517740, 2020).
tumor (continued). "The > 30th CRC group had significantly decreased SFRP2 methylation in tumor area (but not in PBMCs, VAT, and tumor-free area) in comparison with the < 30th CRC group." (PMID 32517740, 2020). "In this study, we found that the promoter methylation level of SFRP1, SFRP2, and WIF1 was enormously higher in tumor tissues than that in adjacent non-tumor tissues." (PMID 31830937, 2019). "We had detected the methylation of SFRP1, SFRP2, and WIF1 for 187 adjacent non-tumor tissue specimens and 307 primary tumor tissue specimens." (PMID 31830937, 2019). "Several angiogenesis-related genes like MMP1, MMP3, SFRP2, CXCL8, SERPINE1 and TNFAIP6 were up-regulated in tumors with necrosis, as identified among genes differentially expressed between tumor samples with and without necrosis." (PMID 26485755, 2015). "The frequent silencing of SFRP2 by methylation in OSCC, but not in non-cancerous tissues suggests SFRP2 has a potential tumor-suppressing effect in the development of OSCC." (PMID 25189527, 2014). "Consistently, single-cell RNA-seq analysis of nonmalignant tumor tissues and HGOSC tissues was utilized to investigate the distribution of SFRP2 in TME and a novel subset with the highest enrichment of SFRP2 and CAF markers (COL6A1, COL6A2, FAP) was identified." (PMID 38069266, 2023). "Due to its specific expression on the tumor vasculature and the absence of toxicity when treating mice with anti-SFPR2 antibodies, we propose SFRP2 might be a valuable target for vaccination." (PMID 33140138, 2021).